CCN2 (cellular communication network factor 2)
Diseases named in the same sentence as CCN2 in open-access papers (continued):
Sharing a sentence is not in itself a finding about the gene and the disease.
prostate carcinoma (32 papers, 2006 to 2025). A carcinoma that arises from epithelial cells of the prostate gland. "CCN1 and CCN2 have been implicated in responses in breast and prostate cancer cells that include proliferation, migration, survival, and tumorigenesis." (PMID 38545253, 2024). "Further investigations are warranted to elucidate the functional consequences of CCN1 and CCN2 induction in PC‐3 and in other prostate cancer cell lines." (PMID 38545253, 2024). "We established in the current study that both LPA and S1P induce CCN1 and CCN2 protein expression in PC‐3 human prostate cancer cells within 2 h." (PMID 38545253, 2024). "The induction of CCN2 could be a key mechanism by which MMP3 induces transformation and tumor progression, as the stromal expression of CTGF promotes angiogenesis and prostate cancer tumorigenesis." (PMID 32429403, 2020).
scleroderma (31 papers, 2005 to 2025). Scleroderma is a rare autoimmune connective tissue disorder characterized by abnormal hardening of the skin and, sometimes, other organs. "Accumulation of collagen, CCN2 and other extracellular matrix proteins in fibrotic lesions is a hallmark of scleroderma and other fibrotic diseases." (PMID 27584154, 2016). "The BB7 dose‐dependent decrease in Col‐1, αSMA, and CCN2 was more pronounced with the scleroderma cells." (PMID 39800950, 2025). "Overall, the mechanoregulatory roles of CCN2 is a growing topic of interest in scleroderma with various pieces of evidence supporting the notion that it is a crucial factor in maintaining epidermal fibrosis in SSc." (PMID 32640520, 2020). "We previously demonstrated that HGF-induced down regulation of collagen and CCN2 in scleroderma LF is mediated by a MAPK-dependent pathway." (PMID 27584154, 2016). "Levels of CTGF/CCN2 in patients with scleroderma or other fibrotic disorders correlate positively with disease severity." (PMID 24015193, 2013). "Other studies have evaluated the utility of N-terminal CCN2 as a marker of intraocular fibrosis and in scleroderma." (PMID 20053285, 2010). "Scleroderma fibroblasts exhibited significantly elevated Col‐1, αSMA, and CCN2 compared with HC." (PMID 39800950, 2025). "Moreover, enhanced expression of CCN2 by scleroderma fibroblasts is shown to promote collagen gel contraction that is dependent on transcription factors known to communicate mechanical adaptions and cues from the ECM." (PMID 32640520, 2020). "HGF treatment of scleroderma lung fibroblasts as well as HGF treatment of TGFβ-treated normal lung fibroblasts transfected with wild type MET is associated with decreased collagen, connective tissue growth factor (CTGF, CCN2) and smooth muscle α-actin (SMA)." (PMID 27584154, 2016). "For example, a strong correlation between collagen and CCN2 expression levels, and Smad1 activation status was observed in hTERT immortalized scleroderma clones and blockade of Smad1 in scleroderma fibroblasts normalized collagen and CCN2 production by these cells." (PMID 21760921, 2011). "Scleroderma fibroblasts exhibited elevated TGM2 expression, which correlated with increased expression of fibrosis markers (Col‐1, αSMA, and CCN2)." (PMID 39800950, 2025). "Fibroblasts from lesional areas of scleroderma patients possess elevated abilities to contract matrix and produce α−smooth muscle actin (α-SMA), type I collagen and CCN2 (connective tissue growth factor, CTGF)." (PMID 19823586, 2009). "For instance, TGF-β-stimulated SMADs are necessary for the induction of CCN2 expression in normal fibroblasts and basal CCN2 induction in scleroderma fibroblasts, while the maintenance of CCN2 expression is independent of SMADs." (PMID 39495216, 2024). "Indeed, several matricellular proteins, including CCN2, CCN1 (cysteine-rich protein 61), and their cell-adhesive receptor, integrin β1, have been shown to play roles in scleroderma, and such studies are still ongoing." (PMID 22911870, 2012). "CCN2/CTGF increased the expression of extracellular matrix molecules such as type I collagen, fibronectin, and integrin, and was overexpressed in fibroblasts in the dermis of patients with scleroderma or other fibrotic disorders." (PMID 16207372, 2005). "Studies using scleroderma cells revealed that treatment with TGF‐β1, in combination with antibodies BB7 and a pan‐TGF‐β blocking antibody, or in the presence of an ALK5 inhibitor for 48 hours, resulted in a reduction of Col‐1, TNC, CCN2, and αSMA to levels comparable with control cells." (PMID 39800950, 2025). "We also found that IQGAP1 expression could be induced in normal lung fibroblasts when exposed to connective tissue growth factor (CTGF, CCN2); moreover, suppression of IQGAP1 by RNA interference decreases the migration of scleroderma and CTGF-induced normal lung fibroblasts." (PMID 38791282, 2024).
scleroderma (continued). "Scleroderma LF transfected with the D1398G mutant or with the MET WT expressed similar to non-transfected cells basal levels of collagen, SMA, and CCN2." (PMID 27584154, 2016).
systemic sclerosis (31 papers, 2010 to 2025). A chronic disorder, possibly autoimmune, marked by excessive production of collagen which results in hardening and thickening of body tissues. "Human skin biopsies of patients with systemic sclerosis presented elevated CCN2 levels associated with phenotype changes in endothelial cells and induction of senescence markers in fibroblasts." (PMID 40362638, 2025). "The -945GC polymorphism (rs6918698) in the connective tissue growth factor gene promoter (CTGF/CCN-2) has been associated with end organ damage in systemic sclerosis." (PMID 21548990, 2011). "Comprehensive meta-analysis identified several functional single nucleotide polymorphisms (SNPs) in the non-coding regions of the CCN2/CTGF gene increasing risk of abdominal aortic aneurysm, systemic sclerosis, nephropathy in type I diabetes, calcified aortic stenosis, and even human longevity." (PMID 32429045, 2020). "It has been demonstrated that polymorphisms in the CCN2 promoter exist in normal individuals and that increased prevalence of certain polymorphisms may be associated with fibrotic diseases such as systemic sclerosis." (PMID 20053285, 2010). "CCN2 is upregulated in many fibrotic disease processes including hepatic and renal fibrosis, radiation enteritis and systemic sclerosis." (PMID 20053285, 2010). "Interestingly, however, previous studies in systemic sclerosis (SSc) revealed that EVs downregulated CCN2 and TGF-β expression, alleviating excessive fibrosis and preventing ECM over-accumulation." (PMID 40518546, 2025). "Interestingly, CCN2 expression, like S100A9, is increased in the epidermal layers of systemic sclerosis skin, a fibrotic disease state associated with TNIP1 SNPs in patient genomes and TNIP1 protein deficiency in lesional skin." (PMID 32377162, 2020). "Knocking down CCN2 using siRNA reduced expression of pro-fibrotic markers (fibronectin p < 0.01, collagen type I p < 0.05, α-SMA p < 0.0001, TIMP-1 p < 0.05 and IL-6 p < 0.05) in TGF-β-treated lung fibroblasts derived from systemic sclerosis patients." (PMID 33662577, 2021).
atherosclerosis (27 papers, 2006 to 2025). A disease characterized by the build-up of fatty material and calcium deposition in the arterial wall resulting in partial or complete occlusion of the arterial lumen. "Studies have suggested a potential role for CCN2 in chronic inflammatory diseases, such as atherosclerosis, rheumatoid arthritis, inflammatory kidney disease and neuroinflammatory pathologies." (PMID 35038159, 2022). "Increased levels of CCN2 have been described in several pathologies, including cardiovascular diseases like heart failure, pulmonary hypertension, vascular remodeling and atherosclerosis." (PMID 35008801, 2021). "We aimed to explore the effect of the overexpression of CCN3 on CCN1 and CCN2 levels in atherosclerosis." (PMID 24722330, 2014). "CCN1 and CCN2 have been reported to be highly expressed in aortic atherosclerotic plaques of a mouse model of atherosclerosis and human atherosclerotic lesions." (PMID 24722330, 2014). "Interestingly, one of the most used drugs for atherosclerosis treatment, statins, have demonstrated to increase TβRII expression, as well as CCN2 production in cultured VSMCs." (PMID 35008801, 2021). "Consistent with a role for CCN2 in tissue formation and remodeling, CCN2 is induced during angiogenesis, wound healing and tissue repair, and is constitutively overexpressed in cancer, atherosclerosis, arthritis and fibrosis." (PMID 16469114, 2006). "Interestingly, the absence of CCN2 increases susceptibility to aortic aneurysms in angiotensin II-induced hypertension and worsens experimental atherosclerosis." (PMID 39273564, 2024). "In addition to known proatherogenic genes, our RNA-Seq analysis identified 2 potentially new proatherogenic genes, Ccn1 and Ccn2, that may contribute to increased atherosclerosis in F1 females." (PMID 39253968, 2024). "Thus, it is plausible that the increased endothelial Ccn1/Ccn2 expression may affect other cell types such as macrophages to contribute to the exacerbated atherosclerosis in F1 female mice from HCD-fed sires." (PMID 39253968, 2024). "To elucidate the potential role of CCN1 and CCN2 in regulating endothelial cell function related to atherosclerosis, we treated human endothelial cells, HMEC-1 cells, with recombinant human CCN1 or CCN2 proteins." (PMID 39253968, 2024). "CTGF (also known as CCN2) is a matricellular protein that plays important roles in pathobiology of various diseases including fibrotic disease and atherosclerosis." (PMID 28837672, 2017). "In the present study, we observed that the overexpression of CCN3 downregulated gene expression of CCN1 and CCN2, indicating that the three CCN proteins had positive or negative effects in atherosclerosis." (PMID 24722330, 2014).
chronic kidney disease (27 papers, 2011 to 2025). Impairment of the renal function secondary to chronic kidney damage persisting for three or more months. "The N-fragment is the predominant CCN-2 molecule in plasma in healthy subjects and chronic kidney disease patients, while full length CCN-2 is hardly detectable by available techniques." (PMID 27644406, 2016). "The identified genes Txnip, Gpx3, Ccn2, Kap, Umod and Ren1 may be useful biomarkers and should be further analyzed with regard to the transition from acute to chronic kidney disease." (PMID 38791453, 2024). "In human chronic kidney disease (CKD) of diverse etiology, kidney CCN2 overexpression has been found correlated with cellular proliferation and ECM accumulation, both in the glomerular and interstitial areas." (PMID 35204752, 2022). "Previously, we demonstrated that the N-fragment of CCN-2 is primarily eliminated by the kidney resulting in accumulation of circulating N-fragment in chronic kidney disease (CKD)." (PMID 27644406, 2016).
myocardial infarction (26 papers, 2009 to 2024). Gross necrosis of the myocardium, as a result of interruption of the blood supply to the area, as in coronary thrombosis. "Tissue levels of CCN2 has been reported to be substantially increased in models of tissue damage (e.g. acute myocardial infarction) as well as in chronic inflammatory disorders with progressive fibrosis." (PMID 26872261, 2016). "While the distribution and regulation of CCN2 in the heart following myocardial infarction is well described, that of CCN5 is largely unknown." (PMID 34854055, 2022). "The early inflammatory phase following myocardial infarction with soaring levels of TNF-α may provide basis for the delayed increase of CCN5 relative to CCN2." (PMID 34854055, 2022). "Yet, studies of various cardiac disease models (myocardial infarction, chronic pressure overload) in mice with overexpression, knock-down or inhibition of CCN2 have reported divergent results regarding the role of CCN2 in maladaptive remodelling of the chronically overloaded heart." (PMID 26872261, 2016). "CCN1/CYR61 is often studied along with CCN2/CTGF in mice models of cardiac infarction, where both CCNs are induced 12 o 14 weeks after induction of myocardial infarction." (PMID 34063397, 2021). "The mechanisms of the delayed induction of CCN5 relative to CCN2 following myocardial infarction has not yet been resolved." (PMID 34854055, 2022).
ovarian carcinoma (25 papers, 2006 to 2025). A malignant neoplasm originating from the surface ovarian epithelium. "Our results demonstrate that S1P disrupts Hippo signaling by reducing YAP phosphorylation and increasing the expression of CCN1 and CCN2 in both ovarian cancer cells." (PMID 28460443, 2017). "To further investigate the roles of CCN1 and CCN2 in the S1P-induced cell proliferation, we used small interfering RNA targeted knock down approach in two ovarian cancer cell lines." (PMID 28460443, 2017). "However, inconsistent with these results, our previous studies showed that both CCN1 and CCN2 mediate the cellular action downstream of S1P in ovarian cancer cells." (PMID 31731760, 2019). "Our in vitro results suggest that S1P and CCN1/CCN2 may play crucial roles in the development and progression of ovarian cancers." (PMID 28460443, 2017). "To date, the fundamental role of CCN1 and CCN2 in the development of ovarian cancers remains unclear." (PMID 28460443, 2017). "Given the important roles of S1P and Hippo signaling pathway in the tumorigenesis of ovarian cancer, we sought to investigate the effects of S1P on YAP and its downstream effectors CCN1 and CCN2 genes." (PMID 28460443, 2017). "In ovarian cancer cells, S1P functions as an upstream stimulator of the Hippo signaling pathway to promote cell proliferation by inducing nuclear accumulation of YAP followed by upregulation of CCN1 and CCN2." (PMID 31731760, 2019). "Consistent with these clinical data, our experimental results showed that knockdown of the endogenous CCN1 and CCN2 significantly decreased the cell proliferation in EOC cells, indicating that CCN1 and CCN2 might play a pivotal role in the progression and outcome of ovarian cancers." (PMID 28460443, 2017).
Peritoneal Fibrosis (25 papers, 2010 to 2025). Disorder characterized by a wide range of structural changes in PERITONEUM, resulting from fibrogenic or inflammatory processes. "Two recent studies demonstrated that CCN2 inhibition (FG-3019) or deficiency (CCN2 conditional knockout) resulted in the maintenance of peritoneal function in a chlorhexidine gluconate-induced peritoneal fibrosis model by reducing angiogenesis, fibrosis, and inflammation." (PMID 32294968, 2020). "Similar observations have been made in peritoneal mesothelial cells, where LPA induces CCN2/CTGF, which is required for fibroblast cell proliferation and peritoneal fibrosis." (PMID 34435178, 2021). "However, biopsy studies in humans investigating the role of TGFβ1, VEGF, and CCN2 in peritoneal fibrosis and EPS in humans are scarce." (PMID 25384022, 2014). "In early stages of peritoneal fibrosis, only CCN2 expression is slightly increased." (PMID 25384022, 2014). "As CCN2 appears an attractive target for antifibrotic therapy, prospective, longitudinal studies are needed to determine whether the dialysate CCN2 concentration or appearance rate combined with peritoneal transport studies can predict the development of peritoneal fibrosis and sclerosis." (PMID 25384022, 2014). "However, whether longitudinal follow-up of peritoneal CCN2 concentration or appearance rate has any value in predicting the development of peritoneal fibrosis or sclerosis remains to be studied." (PMID 25384022, 2014). "In the current study, we investigated the peritoneal gene expression of CCN2, TGFβ1, and VEGF in different stages of peritoneal fibrosis." (PMID 25384022, 2014). "Therefore, CCN2 may be a more appropriate target to prevent or reduce peritoneal fibrosis." (PMID 25384022, 2014). "We hypothesized that CCN2, TGFβ1, and VEGF are already upregulated in early stages of peritoneal fibrosis and further overexpressed in EPS." (PMID 25384022, 2014). "Therefore, we studied peritoneal expression of CCN2, as well as TGFβ1 and VEGF, in different stages of peritoneal fibrosis." (PMID 25384022, 2014).
endometriosis (23 papers, 2013 to 2025). The growth of functional endometrial tissue in anatomic sites outside the uterine body. "Furthermore, the decrease in miR-214-3p expression was associated with the inhibition of endometriosis lesion fibrosis through the targeting of connective tissue growth factor (CCN2)." (PMID 41301870, 2025). "Exosomal miR-214-3p inhibits the process of endometriosis fibrosis by regulating connective tissue growth factor (CCN2)." (PMID 36548867, 2022). "They reported that exosomal miR-214-3p suppresses endometriosis fibrosis by regulating connective tissue growth factor (CCN2) as an important factor in fibrogenesis." (PMID 33671587, 2021). "CTGF, also known as CCN family protein 2 (CCN2), has been identified as an important fibrotic marker in endometrial diseases including endometriosis and intrauterine adhesions." (PMID 31101053, 2019).